IL6 (interleukin 6)
Diseases named in the same sentence as IL6 in open-access papers (continued):
Sharing a sentence is not in itself a finding about the gene and the disease.
tumor (continued). "Research has demonstrated that IL-6 expedites tumor cell proliferation by upregulating cyclins, downregulating the expression of the cyclin-dependent kinase inhibitor p21, and activating STAT3 protein." (PMID 40563367, 2025). "Using a ketogenic infant formula (KF), researchers found that colon tumor-bearing mice fed KF exhibited preserved body and muscle mass, reduced tumor weight, and lower plasma IL-6 levels compared to controls." (PMID 41398969, 2025). "First, an increase in forward scatter CV after Pam3CSK4 stimulation suggests WBC hyperactivity, which can lead to the release of cytokines and chemokines like TNF, IL-6, and IL-8, promoting tumor cell proliferation, invasion, and metastasis." (PMID 39960903, 2025). "The recent discoveries showed that the blockage of IL-6 signaling enhances the anti-tumor effect of STING-targeting therapies." (PMID 39857957, 2025). "STAT3 is the main downstream regulator of IL6 signal transduction and plays a unique role in regulating inflammation and tumor transformation." (PMID 40841364, 2025). "High levels of IL-6 in the TME promote tumor cell proliferation, survival, and invasiveness through the IL-6/JAK/STAT3 signaling pathway." (PMID 40430040, 2025). "As pivotal orchestrators within the TME, CAFs establish a pathological ecological network that supports tumor progression through the secretion of cytokines such as IL‐6, TGF‐β, and CXCL12." (PMID 41164803, 2025). "Preliminary studies have shown that nanoparticles carrying TNF-α inhibitors or IL-6 blockers can localize treatment to the tumour site, thereby increasing the therapeutic window while reducing toxicity." (PMID 40544399, 2025). "Hailemichael suggests that IL-6 blockade abrogates immunotherapy toxicity and promotes tumor immunity." (PMID 40919167, 2025). "IL-6 promotes CRC cell proliferation and survival via the JAK/STAT3 pathway and is associated with tumor growth and poor prognosis." (PMID 40725273, 2025). "In immune cells, STAT3 signaling encourages autocrine production of IL-6 that sustains tumor-promoting inflammation along with immunosuppressive factors such as IL-10 and TGFβ which blunt the anti-tumor response." (PMID 40356899, 2025). "IL-6, a pro-inflammatory cytokine produced by diverse cell types, including tumor cells and inflammatory cells, drives tumorigenesis and progression through multiple molecular pathways." (PMID 40563367, 2025). "Immune modulation: Tumour-derived EVs containing miR-21 and miR-29a bind Toll-like receptors (TLR7/8) on immune cells, triggering an NF-κB–mediated inflammatory cascade (↑TNFα, IL-6) that promotes tumour growth and metastasis." (PMID 41311647, 2025). "In turn, results from other authors have shown that higher IL-6 expression correlates with metastasis, angiogenesis, greater tumor cell proliferation, and larger tumor size." (PMID 41007818, 2025). "Pro-inflammatory cytokines, including IL-2, TNFα, IL-1β, and IL-6, contribute to shaping a tumor-promoting microenvironment by sustaining inflammation and facilitating cancer cell survival and dissemination." (PMID 41614846, 2025). "In DCs, the activation of the IRF3/IFN-I signaling cascade promotes antitumor activity, whereas the NF-κB/IL-6/STAT3 axis activation escalates tumor progression." (PMID 41176596, 2025). "IL-6, a pivotal tumor-promoting cytokine, induces CCL2 secretion via STAT3 activation; the two engage in macrophage-mediated feedback amplification." (PMID 41341593, 2025). "IL-6 blockade not only induces immunogenic cell death in tumor cells but also reprograms TAMs toward an anti-tumoral phenotype, effectively reversing resistance to ICIs while minimizing immune-related adverse events." (PMID 41417432, 2025). "As another key factor of the SASP, IL-6 can not only promote tumorigenesis and cell proliferation but also exert tumor-suppressive functions depending on the cellular context." (PMID 40563707, 2025).
tumor (continued). "IL-6 is among the cytokines the inflammasome released from necrotic cells into the tumor microenvironment." (PMID 41068541, 2025). "IL-6 is a multifunctional inflammatory cytokine secreted by a variety of cells including macrophages, monocytes, fibroblasts and tumor cells." (PMID 41376630, 2025). "We noted that TUBA1B overexpression is linked to key immune-related pathways in the tumor immune microenvironment (TIME), such as IL-6/JAK/STAT3 signaling, IL-2/STAT5 signaling, TGF-Beta signaling, and interferon responses." (PMID 39968182, 2025). "Our data suggest that the antitumor efficacy of TGFβ-specific T cells in PC depends on the presence of IL-6 within the tumor." (PMID 39653766, 2025). "Compared with paired surgical margins, tumour tissues exhibited an inflammatory shift characterised by increased IL-1β and IL-6 alongside reduced TNF-α, IFN-γ, IL-12 and IL-2." (PMID 41465261, 2025). "On the other hand, IL-6 plays a crucial role in chronic inflammation, favoring a pro-inflammatory tumor microenvironment that contributes to cell proliferation and survival, as well as metastasis." (PMID 40004863, 2025). "In the present study, inhibition of IL‐6 when combined with eribulin synergistically suppressed tumor progression in a PDX model." (PMID 41189442, 2025). "Whereas iCAFs are prone to filling gaps between nests of tumor cells and releasing inflammatory cytokines such as interleukins IL-1 and IL-6." (PMID 40523922, 2025). "Intracranial SB28 tumor-initiating capacity was reduced in C57BL/6J Il-6 knockout mice compared to wild-type mice." (PMID 40161763, 2025). "These cytokines represent complementary aspects of the tumor microenvironment: pro-inflammatory and tumor-promoting signaling (IL-6, IL-1β, TNF-α), anti-inflammatory modulation (IL-10), and Th17-driven immune activity (IL-17)." (PMID 41267807, 2025). "The engineered population, designated LAMΦ-M7/8a, demonstrated the ability to phagocytose 4T1 tumor cells and secrete high levels of IL-6 and TNF-α in vitro." (PMID 41417432, 2025). "For instance, Fusobacterium nucleatum has been shown to modulate the tumor microenvironment by inducing the expression of pro-inflammatory cytokines such as IL-6, IL-17, and tumor necrosis factor α, which promote angiogenesis and tumor cell metastasis." (PMID 40110192, 2025). "Our results demonstrated that IL-6, IL-1β, and IL-10 were overexpressed in tumor tissues compared with normal mucosa." (PMID 41267807, 2025). "A positive feedback loop between NF-κB and pro-inflammatory mediators, particularly tumour necrosis factor-alpha (TNF-α), interleukin-6 (IL-6), and IL-1β, further amplifies chronic inflammation, perpetuating a tumour-promoting microenvironment." (PMID 40076898, 2025). "The tumour microenvironment has signals also derived from the tumour microenvironment, such as CXCL12, TGF-β, and IL-6, that can promote tumour survival and chemoresistance." (PMID 41002447, 2025). "Inflammation and cytokine release: Neutrophils release cytokines (e.g. IL-6, IL-8) that promote tumor cell proliferation and survival." (PMID 41180630, 2025). "Its anticancer mechanism included triggering apoptosis and necrosis by elevating intracellular reactive oxygen species (ROS) levels and decreasing IL-6 in tumor cells." (PMID 39861135, 2025). "This miR‐16 suppresses CSF‐1 and CCL‐2 expression, reprogramming tumor‐associated macrophages (TAMs) via reduced TGF‐β and IL‐6 levels and elevated TNF‐α through the NF‐κB pathway." (PMID 40079186, 2025). "Through STAT3 and STAT6 activation, IL-6 stimulates M2 macrophage polarization, tumor growth, and immune suppression." (PMID 41350724, 2025). "Our findings showed a significant increase in IL6 gene expression, which correlated with the Fusobacterium load in the tumor biopsies." (PMID 40895532, 2025). "IL-6 is a protein that tumor cells always produce; other proteins are only produced in response to certain stimuli." (PMID 41179937, 2025).
tumor (continued). "Specifically, IL‐6 has been shown to support tumor progression by acting directly on cancer cells and by promoting immune tolerance through the expansion of myeloid‐derived suppressor cells (MDSCs)." (PMID 41189442, 2025). "IL-6 triggers tumor progression by promoting tumor cell proliferation, survival, EMT, angiogenesis, and chemoresistance." (PMID 40165901, 2025). "In this study, establishing a correlation between IL-6 levels at various time points and tumor progression or prognosis was more challenging than analyses based solely on initial values." (PMID 39781345, 2025). "Serum IL-6 levels are thought to be involved in the suppression of tumor immunity and are useful in predicting the therapeutic effect of Atezo+Bev treatment." (PMID 39652104, 2025). "PD-L1 is highly glycosylated in tumor cells to maintain its stability via IL-6/JAK1-mediated phosphorylation and subsequent glycosylation." (PMID 39996058, 2025). "M1 macrophages, often referred to as “classically activated” macrophages, produce pro-inflammatory cytokines such as TNF-α, IL-1β, and IL-6, as well as nitric oxide (NO), and exhibit strong anti-tumor activity." (PMID 40328748, 2025). "Lipid-accumulated antigen-presenting cells have diminished capacity to prime anti-tumor T cells, and lipid-conditioned TAMs secrete factors (e.g., IL-6, TGF-β) that further dampen T-cell immunity." (PMID 41209556, 2025). "Specifically, NSCLC cells activate the IRE1α arm of the UPR pathway in response to stressors in the tumor microenvironment, which in turn promotes IL-6 secretion." (PMID 41254082, 2025). "(I) FACS analysis of intracellular IL-6 in tumor-infiltrated myeloid cells and macrophages from tumors in A. Data are represented as the mean ± SD." (PMID 40920087, 2025). "IL-6 has dual roles in tumors, with chronic activation promoting tumor progression and acute activation having anti-tumor effects." (PMID 41476977, 2025). "When it comes to interleukins, tumor cells secrete IL-6, which binds to IL-6 receptor and Glycoprotein 130 (GP130) on MSCs." (PMID 41471830, 2025). "Tumor-derived exosomes were internalized by macrophages in axillary lymph nodes, inducing IL-6 expression." (PMID 40103824, 2025). "TAMs generally exhibit two polarization states: M1 (classically activated, tumoricidal) enhance antitumor immunity by secreting TNF‐α, IL‐1β, and IL‐6, and producing nitric oxide and ROS, directly killing tumor cells and inhibiting tumor growth." (PMID 40900811, 2025). "Due to the tumor immunosurveillance function of microglia in brain tissue, we then detected the expression of cytokine IL6 and chemokine CCL2 in BC-BM brain tissue." (PMID 40444044, 2025). "The suppression of IL-6 in these patients has shown not only direct inhibition for tumor neogenesis but also changes in the stromal profile into an antitumor one." (PMID 40149994, 2025). "The COX2/PGE2 axis also enhances IL-6 secretion from macrophages, exacerbating inflammation and further promoting tumor progression." (PMID 40909271, 2025). "In this study, MCF-7 cells in the presence of CV extract significantly decreased LPS-stimulated secretion of interleukin-6 (IL-6), a cytokine known to promote tumour proliferation, survival and metastasis." (PMID 41150756, 2025). "Metformin has also been reported to down-regulate PD-L1 on tumor cells via the IL-6/JAK2/STAT3 pathway." (PMID 41374963, 2025). "Similar evidence has been collected in glioblastoma models, where tumor‐derived IL‐6 activates STAT3 signaling to initiate senescence in peritumoral macrophages rather than TAMs." (PMID 41427020, 2025). "PSCs release IL-6 to cross-talk with tumor cells, activating STAT3 signaling and promoting invasive phenotypes." (PMID 40948749, 2025). "Cytokines and growth factors, such as interleukin-6 (IL-6), interleukin-8 (IL-8), and tumor necrosis factor-alpha (TNF-α), are often elevated in the saliva of patients with OSCC, indicating tumor-associated inflammation." (PMID 41502517, 2025).
tumor (continued). "Tumor‐derived GM‐CSF, IL‐6 and VEGF‐A attract MDSCs, which inhibit T‐cell responses via TGF‐β, IL‐10, arginase (ARG)‐1 and reactive oxygen species." (PMID 41143064, 2025). "Trials are currently underway testing IL6 and PD-1 pathway inhibitor combinations for improved anti-tumor efficacy and irAEs (NCT03999749, NCT04258150)." (PMID 39663510, 2025). "Within the tumor microenvironment, interleukin-6 and integrin ανβ6 are critical factors that contribute to the accumulation of mutations, thereby facilitating the progression of cancer." (PMID 40183091, 2025). "Among TAMs released factors, IL-6, IL-10 and IL-8 foster signaling pathways directly involved in stimulating cancer cell proliferation and tumor growth." (PMID 39981232, 2025). "The downstream effects of NF-κB include increasing the production of IL-6 and enhancing tumor cell proliferation and survival through auto/paracrine IL-6/sIL-6R trans-signaling." (PMID 40697656, 2025). "IL-6 and IL-10 levels, which are known to promote PCs proliferation, also promote the development of the NK-resistant tumor phenotype by inhibiting their activity." (PMID 40755766, 2025). "In our experiments, the interaction of anti‐ROR1 CAR T‐cells with ROR1‐expressing tumor cells in the IAC model was associated with the release of proinflammatory cytokines, including TNF, IL‐6, and IFN‐γ." (PMID 40249196, 2025). "Spatial mapping localizes TMEM106A to peri‐necrotic and microvascular regions, niches that accumulate tumor‐associated macrophages (TAMs) in GBM and align with IL‐6–enriched inflammation." (PMID 41354084, 2025). "This is in line with previous studies that reported diminished cytokine and chemokine production, reduced tumour growth, tumour immune infiltrate and angiogenesis following IL‐6 blockage." (PMID 39245677, 2025). "In the “any tumor vs. control” analysis, apoptosis emerged as the best-performing biomarker (AUC = 0.895), followed by IL-6 (AUC = 0.832) and CA125 (AUC = 0.812), all of which showing excellent sensitivity and specificity rates." (PMID 41149076, 2025). "In contrast, iCASs are identified at distant locations from the tumor and are responsible for secreting inflammatory cytokines, the most abundant being IL-6." (PMID 40427098, 2025). "IL-6 is a multifunctional cytokine mainly produced in the tumor microenvironment and is a key factor driving tumor growth and metastasis." (PMID 40839565, 2025). "Future studies should explore the integration of inflammatory markers (e.g., CRP, IL-6), tumor-intrinsic features, or functional immune assays to enhance prediction accuracy in chemotherapy-treated patients." (PMID 40958865, 2025). "IL-6 has been demonstrated to influence tumor initiation and progression by affecting a number of factors, including but not limited to: tumor cell survival, proliferation, invasion, and the tumor microenvironment." (PMID 41291543, 2025). "The term metabolic reprogramming began to explode in 2021, lactic acid stimulates the secretion of IL-6 and VEGF by tumor-associated adipocytes through activation of GPR81, thereby further promoting tumor growth." (PMID 40416986, 2025). "For patients with tumors, tumor cells release a variety of cytokines such as interleukin‐1 (IL‐1), IL‐6, and TNF‐α, which can stimulate osteoclast differentiation via multiple mechanisms and disrupt the balance of bone remodeling." (PMID 40989575, 2025). "The strong correlation between inflammation and cancer is demonstrated by the elevated levels of IL‐6 in the tumor microenvironment." (PMID 39803280, 2025). "Hypoxia directly impairs the function of tumor-infiltrating lymphocytes (TILs) and upregulates immunosuppressive signals such as PD-L1, TGF-β, IL-6, and IL-10 within the tumor microenvironment." (PMID 40260303, 2025). "Tumor-derived cytokines, notably IL-6 and tumor necrosis factor α (TNF-α), contribute to adipose tissue inflammation, impairing insulin sensitivity." (PMID 41397158, 2025).
tumor (continued). "The study found that OP bone fragments increased the release of pro-inflammatory cytokines, such as TNF-α, IL-6, IL-1β, and IL-8, which regulate immune cell activity in the tumor microenvironment." (PMID 40584290, 2025). "In our direct co-cultures, we observed an early increase in IFN-γ secretion and enhanced tumor cell killing activity, followed by a decrease in IL-1β, IL-4 and IL-6 levels alongside an increase in soluble CXCL1." (PMID 40108668, 2025). "The increase in IL-6 levels within the tumor following TGFβ vaccine treatment was corroborated by immunofluorescence, providing direct visualization of elevated IL-6 in the tumor microenvironment." (PMID 39653766, 2025). "Given the complexity of the OCCC TME, therapeutic strategies that combine ICIs with agents targeting key molecules implicated in tumor aggressiveness such as VEGF, HIF-1α, IL-6, IL-10, PI3K, and HDAC6 show considerable promise." (PMID 41383608, 2025). "The shift in SASP from tumor suppression to promotion remains poorly understood, with IL-6 and IL-8 playing key roles." (PMID 40277933, 2025). "The dramatic increase in soluble IL-6 needs further investigation, given the dual role that IL-6 plays in the tumor microenvironment." (PMID 40124384, 2025). "Upon ligand-receptor binding, tumor-derived IL-6 plays a crucial role in promoting MDSC chemotaxis within the TIME by activating the JAK/STAT3 and NF-κB signaling pathways." (PMID 41326342, 2025). "It is known that IL-6 is a mediator of tumorigenesis in several human malignancies, being overactive in many tumor types, including GC, and that the aberrant activation of the JAK/STAT pathway being dependant on IL-6 dictates development and resistance in GC." (PMID 40141175, 2025). "The qPCR analysis of total mRNA from tumor tissues revealed significant upregulation of M1 markers Nos2, Il1b, and Il6, along with marked downregulation of M2 markers Mcr1, Arg1, and Il10." (PMID 39908200, 2025). "Interleukin-6 (IL-6), a key growth factor for B cells, supports tumor growth and metastasis through its secretion by DLBCL cells and the surrounding stroma." (PMID 40881684, 2025). "Tumor-derived factors such as GM-CSF, G-CSF, and IL-6 promote myeloid differentiation and induce myeloid precursors to differentiate into MDSCs with suppressive properties." (PMID 41368628, 2025). "Following the injection of IL-6, there was a notable increase in both tumor volume and weight and the injection of either IL-6+GA or IL-6+DDP partially reduced tumor volume and weight." (PMID 40486873, 2025). "In a metastatic RCC there is evidence that IL-6 levels are greatly increased as part of the tumour milieu to promote evasion of the adaptive immune response by arresting dendritic cell processing and leading to increased intracellular STAT3 signaling." (PMID 40610926, 2025). "Elevated TNF (Tumor Necrosis Factor) and IL-6 (Interleukin 6) drive chronic inflammation, further promoting tumor development." (PMID 41562760, 2025). "At the same time, IL-6 and TNF-α secreted by TAMs (tumor-associated macrophages) promote ROS accumulation through NOX2 activation, forming a vicious cycle of oxidative stress-ferroptosis." (PMID 40535125, 2025). "IL-6 enhances immune cell recruitment and promotes tumor progression by inducing epithelial-to-mesenchymal transition (EMT) and angiogenesis, while IL-1β and IL-18 are key pro-inflammatory cytokines activated by the NLRP3 inflammasome pathway." (PMID 40218944, 2025). "GSEA hallmark analysis also revealed that hallmarks of interferon-gamma response and IL6_JAK_STAT3 pathway were downregulated in old tumor cells." (PMID 41332581, 2025). "Chronic inflammatory signaling can create a tumor-promoting microenvironment, with interleukins, such as IL-6, IL-8, IL-10, and IL-17, acting as central mediators." (PMID 40725273, 2025).